ENSG00000287087 (novel transcript, antisense to ARL15)
Gene: Long non-coding RNA gene on chromosome 5 (53,897,464 to 53,899,370, forward strand). Ensembl gene ENSG00000287087.
Gene Ontology:
Biological process: SRP-dependent cotranslational protein targeting to membrane, signal sequence recognition
Cellular component: signal recognition particle, endoplasmic reticulum targeting